SDC1 (syndecan 1)
Diseases named in the same sentence as SDC1 in open-access papers (continued):
Sharing a sentence is not in itself a finding about the gene and the disease.
colitis (14 papers, 2013 to 2026). Inflammation of the colon. "For this investigation, we applied the AOM-DSS mouse model in Sdc1 KO and wt mice and demonstrated that Sdc1 deficiency resulted in increased susceptibility to colitis-associated tumorigenesis." (PMID 28350804, 2017). "Sdc1 deficiency profoundly affected the chronic phase of DSS-induced colitis, as demonstrated by differences in the extent of weight loss and inflammation severity score between the groups." (PMID 28350804, 2017). "In syndecan-1-deficient mice after colitis induction, delayed skin and corneal wound healing, functionally adverse repair, prolonged recruitment of inflammatory cells, and significant upregulation of TNFα were detected." (PMID 23874391, 2013). "Importantly, colitis-associated tumors developed in Sdc1-defficient mice were characterized by increased local production of IL-6, activation of STAT3, as well as induction of several STAT3 target genes that act as important effectors of colonic tumorigenesis." (PMID 28350804, 2017). "Furthermore, LMWH ameliorates the inflammatory response of experimental colitis in syndecan-1-deficient mice." (PMID 23874391, 2013). "Deficiency in syndecan-1 contributes to the increased severity of DSS colitis, which promotes delayed wound repair and re-epithelialization, and the function of syndecan-1 could be restored with heparin treatment." (PMID 23874391, 2013). "Moreover, it has been demonstrated that LMWH ameliorates the inflammatory response in experimental colitis in rats and syndecan-1-deficient mice." (PMID 23874391, 2013). "And the results document a significant correlation between SDC1 shedding and the regulation of inflammation in colitis patients’ samples and intestinal epithelial cells." (PMID 27558380, 2017). "In contrast, the colitis symptoms were substantially relieved in the DSS plus wt‐SDC1 and DSS plus mut‐SDC1 groups." (PMID 27558380, 2017). "Role of membrane SDC1 in inflammatory pathway, pro‐inflammatory cytokine secretion as well as neutrophil transmigration, and how suppressing its shedding will benefit colitis were further investigated." (PMID 27558380, 2017). "Suppression of SDC1 shedding in intestinal epithelial cells plays an anti‐inflammatory role, ameliorates colitis and thus is helpful for this disorder treatment." (PMID 27558380, 2017). "Suppressing shedding of SDC1 from intestinal epithelial cells plays an anti-inflammatory role in ameliorating colitis and thus is helpful for colitis treatment." (PMID 27579035, 2016). "The mucosal SDC-1 was shown to decrease and serum SDC-1 levels were shown to increase in parallel with the severity of histopathological damage in IBD mostly in experimental colitis models." (PMID 26294905, 2015). "Sdc-1 gene deletion in mice reduces inflammation in models of allergic contact dermatitis, allergic lung disease, colitis and nephritis, with increased leukocyte recruitment and more severe disease." (PMID 25015005, 2014). "Consistent with previous results, we found that the mRNA and protein expression of syndecan-1 in the colonic mucosa of DSS-induced colitis was greatly decreased, while the syndecan-1 level in serum was much greater." (PMID 23874391, 2013). "LMWH has therapeutic effects on colitis by downregulating inflammatory cytokines and inhibiting syndecan-1 shedding in the intestinal mucosa." (PMID 23874391, 2013). "We found that syndecan-1's mRNA and protein expression in the colonic mucosa of DSS-induced colitis mice was gradually decreased, while the levels of IL-1β and the free syndecan-1 ectodomain in the serum were increased." (PMID 23874391, 2013). "In this study, we found that the mRNA expression of IL-1β was inversely correlated with syndecan-1 in the intestinal mucosa of DSS-induced colitis." (PMID 23874391, 2013). "In this study, we found that LMWH downregulated the levels of IL-1β and IL-10 in colitis mucosa, reduced the shedding of syndecan-1, and ameliorated colitis induced by DSS." (PMID 23874391, 2013).
colitis (continued). "To evaluate the involvement of syndecan-1 in LMWH-mediated alleviation of colitis, we examined the expression of syndecan-1 in the intestinal mucosa at both the mRNA and protein levels by qRT-PCR and immunohistochemistry, respectively." (PMID 23874391, 2013). "Furthermore, Bmp4+ fibroblasts in the berberine group exhibited enhanced collagen-Sdc1/4 signaling, a pathway critical for modulating epithelial barrier integrity and promoting mucosal regeneration in experimental colitis 50,51." (PMID 41356191, 2026). "Moreover, SDC1 ameliorated colitis activity and improved histological disturbances of colon in mice." (PMID 27558380, 2017). "Taken together, these results indicate the loss of syndecan-1 and intestinal mucosal damage in the colonic mucosa of DSS-induced colitis, while the loss of syndecan-1 and histological lesions could be restored partially by LMWH treatment." (PMID 23874391, 2013). "In the DSS plus LMWH group, LMWH could ameliorate the disease activity, relieve histopathological disturbances of DSS-induced colitis, inhibit syndecan-1 shedding, and increase the protein and mRNA levels of syndecan-1." (PMID 23874391, 2013). "Further investigation of the role of syndecan-1 shedding in the pathogenesis of colitis is needed." (PMID 23874391, 2013). "Moreover, SDC1 also has a protective effect during experimental colitis." (PMID 27558380, 2017). "To further investigate the effects of SDC1 on intestinal inflammation in vivo, we introduced the mouse model of DSS‐induced colitis." (PMID 27558380, 2017). "In the majority of experimental colitis models and human studies conducted to date, mucosal SDC-1 levels were shown to be lower and serum SDC-1 levels higher in IBD compared to the normal population." (PMID 26294905, 2015). "Thus, we hypothesized that syndecan-1 may be involved in the inflammation of colitis." (PMID 23874391, 2013).
myocardial infarction (14 papers, 2014 to 2026). Gross necrosis of the myocardium, as a result of interruption of the blood supply to the area, as in coronary thrombosis. "Deposition of the complement components C3d and C5b-9 was seen in reperfused hearts of myocardial infarction patients and associated with an increase in shedding of syndecan-1, a core protein of the endothelial glycocalyx." (PMID 35647072, 2022). "Syndecan-1 is mainly known as a pro-fibrotic player and regulator of immune cell infiltration after a myocardial infarct." (PMID 32984315, 2020). "Other research studies highlighted that in acute myocardial infarction, there are elevated serum levels of syndecan-1, due to an increased sympatho-adrenergic activation and subsequent damage to endothelial glycocalyx." (PMID 31815014, 2019). "In a mouse myocardial infarction model increased sdc1 expression reduced cardiac dilatation and dysfunction." (PMID 31797997, 2019). "Roles of syndecan-1 and -4 have been explored in myocardial fibrosis and have been found to be crucial for “wound healing” and scar formation following myocardial infarctions." (PMID 31547598, 2019). "Multiple evidence revealed that syndecan-1 is also associated with tissue injury and may regulate inflammatory and regenerative responses, being considered a protective molecule that limits the inflammation and reduces cardiac remodelling and dysfunction after a myocardial infarction." (PMID 31815014, 2019). "For example, in a mouse model of myocardial infarction, Sdc1-/- mice had elevated leukocyte recruitment and increased matrix metalloproteinase activity with increased collagen fragmentation and disorganization." (PMID 26832929, 2016). "In another study, it was hypothesized that these effects may also be mediated by regulation of TGFβ signalling by syndecan-1, with an enhanced anti-inflammatory response in myocardial infarction, in contrast to the profibrotic action exhibited in Ang II-treated hearts." (PMID 31815014, 2019).
coagulopathy (12 papers, 2017 to 2026). "Endotheliopathy represented by SDC-1 elevation was associated with trauma induced coagulopathy, which can lead to the development of DIC." (PMID 37445421, 2023). "We further measured the soluble form of syndecan-1, a transmembrane core protein of the glycocalyx whose shedding is associated with coagulopathy." (PMID 34830227, 2021). "TBI-associated coagulopathy was associated with significant elevations in plasma syndecan-1, a surrogate marker of glycocalyx degradation (endotheliopathy of trauma), whilst thrombomodulin levels did not vary significantly." (PMID 29337920, 2018). "Post-trauma elevations in syndecan-1 levels have been associated with coagulopathy and mortality, suggesting that degradation of the endothelial glycocalyx may contribute to the development of ATIC." (PMID 29337920, 2018). "Therefore, we recommend measuring syndecan-1 to identify endotheliopathy-associated early coagulopathy following brain trauma." (PMID 29337920, 2018). "Since cfDNA, thrombomodulin, and syndecan-1 have all been shown to be associated with coagulopathy, a finding that was confirmed in the current study, they represent possible sources of further information (in addition to viscoelastic assays) to the trauma clinician during resuscitation." (PMID 29261771, 2017). "In patients with trauma, succinate levels were associated with glycocalyx damage and the development of coagulopathy, and the interaction of MMP24 and syndecan-1 was elevated compared to healthy controls." (PMID 37315138, 2023). "We determined our cut-off level of ≥30.5 ng/mL as the level of syndecan-1 for prediction of early coagulopathy as the outcome (area under the curve = 0.62; 95% Confidence interval (CI) 0.50 to 0.72)." (PMID 29337920, 2018). "Using ROC analysis (area under the curve = 0.61; 95% Confidence Interval (CI) 0.50 to 0.72), we established a plasma syndecan-1 level cutoff of ≥30.5 ng/mL (sensitivity % = 55.3, specificity % = 52.3), with a significant association with TBI-associated coagulopathy." (PMID 29337920, 2018). "The syndecan-1 concentrations were higher in patients developing coagulopathy, but this increase was not significant." (PMID 39597912, 2024). "Also, significantly elevated plasma syndecan-1 levels were seen in patients who developed early coagulopathy (33.7(21.6–109.5) ng/mL) as compared to those who did not (29.9(19.2–39.5) ng/mL; p = 0.03), and the control group (p = 0.04)." (PMID 29337920, 2018). "The primary objective of this study was to study the difference in syndecan-1 and soluble thrombomodulin (sTM) levels in severe isolated TBI patients with/without early coagulopathy." (PMID 29337920, 2018).
endometriosis (12 papers, 2014 to 2025). The growth of functional endometrial tissue in anatomic sites outside the uterine body. "It has been reported that certain soluble cell adhesion molecules and co-proteins (sICAM-2, -3, -4, and syndecan- 1, -4) are involved in the formation and development of endometriosis." (PMID 39991572, 2025).
pulmonary fibrosis (12 papers, 2010 to 2025). Chronic progressive interstitial lung disorder characterized by the replacement of the lung tissue by connective tissue, leading to progressive dyspnea, respiratory failure, or right heart failure. "That study indicated that syndecan-1 controls epithelial cell plasticity and pulmonary fibrosis by altering EV miRNA profiles that can regulate fibrogenic signaling pathways, such as TGF-β and WNT signaling." (PMID 35909143, 2022). "When EVs isolated from BALF of fibrotic lungs (F-EVs) were re-instilled intratracheally into the BLM-fibrosis-mouse model (WT and Sdc1−/−), they showed that F-EVs exacerbated lung fibrosis in the WT-BLM-mouse model in comparison with Sdc1−/− animals." (PMID 36232350, 2022). "Regarding syndecans, soluble syndecan-1 ectodomain has been reported to cause neutrophil chemotaxis and aberrant wound healing in asbest and BLM-induced pulmonary fibrosis models, showing the pro-fibrotic activity of syndecan-1." (PMID 31600983, 2019). "Syndecan‐1 also contributes to neutrophil chemotaxis: shed and exogenous SDC1 ectodomain induces neutrophil chemotaxis, inhibits epithelial wound healing and promotes fibrogenesis in a mouse model of idiopathic pulmonary fibrosis." (PMID 27558380, 2017). "In parallel, increased accumulation of heparan-sulfate (HS) PGs such as syndecan 1 are also observed in bleomyin-induced lung fibrosis and in human idiopathic pulmonary fibrosis (IPF)." (PMID 26751072, 2016). "SDC1 contributes to neutrophil chemotaxis; shed and exogenous SDC1 ectodomain can induce neutrophil chemotaxis, inhibit epithelial wound healing, and promote fibrogenesis in mouse model of idiopathic pulmonary fibrosis." (PMID 27579035, 2016). "Previous studies have shown that shedding of syndecan-1, a heparin sulfate proteoglycan highly abundant in the extracellular matrix, occurs in models of pulmonary fibrosis." (PMID 20333255, 2010). "In pulmonary fibrosis, syndecan-1 overexpression and shedding were found to contribute to neutrophil chemotaxis, impair alveolar epithelial repair, and drive fibrosis through TGFβ and Wnt signaling, highlighting a common pathological mechanism between the two conditions." (PMID 40136525, 2025). "Finally, they found that mice treated with Sdc1−/− EVs had reduced lung fibrosis compared with those receiving WT-EVs." (PMID 36232350, 2022).
cardiac arrest (11 papers, 2015 to 2025). Cessation of breathing and/or cardiac function. "Such a role has also been demonstrated for syndecan-1, which is shed during ischemic conditions of the heart causing endothelial damage, e.g., cardiac arrest, chronic heart failure and microvascular occlusions in ST elevation MI." (PMID 37189684, 2023). "Syndecan-1 levels peaked 24 h after cardiac arrest, whereas hyaluronic acid levels peaked only after 48 h." (PMID 40943808, 2025). "The different time course of changes in the respective glycocalyx components is in accordance with a recent study on glycocalyx shedding after cardiac arrest, in which a correlation between shedding of Syndecan-1 and hyaluronic acid and death was observed." (PMID 40943808, 2025). "The endothelial glycocalyx has also been implicated in post-cardiac arrest syndrome in adults, indicating that cardiac arrest or resuscitations can shed the glycocalyx components syndecan-1, HS, and HA into blood circulation." (PMID 34573906, 2021). "Syndecan-1 serum levels were higher in patients suffering from multiple organ failure 0 h-48 h after cardiac arrest." (PMID 31148947, 2019). "In contrast to IL6, we found that syndecan-1 is still being released at 24 h, hypothetically due to other factors than the initial cardiac arrest-induced ischemic insult, like further persistent shock states or aggressive vasopressor and fluid treatment." (PMID 31148947, 2019). "Additionally, syndecan-1 levels significantly increased in rats with cardiac arrest on VA-ECMO support compared to baseline (before cardiac arrest)." (PMID 39409009, 2024). "Syndecan-1 was reported to increase up to 100-fold in trauma patients, 65-fold in patients undergoing major vascular surgery with global and regional ischemia, 8-fold in septic patients, and 3- to 4-fold after cardiac surgery or after resuscitated cardiac arrest." (PMID 32576151, 2020). "Additionally, patients who survive cardiac arrest have lower HS and syndecan-1 levels than deceased patients, indicating that the extent of glycocalyx perturbation and corresponding levels of GAGs in blood could indicate prognosis in these adult patients (n = 25)." (PMID 34573906, 2021). "Cardiac arrest and ECPR led to a considerable increase in plasma syndecan-1 levels at 120 min." (PMID 34781966, 2021). "Syndecan-1 levels showed the undulant values without significant changes within 48 h after cardiac arrest." (PMID 31148947, 2019). "Syndecan-1 serum levels were higher in nonsurvivors 0 h-12 h after cardiac arrest." (PMID 31148947, 2019).
heart failure (11 papers, 2013 to 2025). Inability of the heart to pump blood at an adequate rate to meet tissue metabolic requirements. "A previous study has also reported that syndecan-1 concentration was associated with clinical outcomes in patients with heart failure and with preserved ejection fraction." (PMID 34879094, 2021). "• Circulating levels of adrenaline and syndecan-1 were associated independently with mortality and heart failure." (PMID 23433357, 2013). "Additionally, a doubling of syndecan-1 levels was associated with an increased risk of all-cause mortality and rehospitalization for heart failure, in patients with CHF with preserved ejection fraction." (PMID 34073616, 2021). "Moreover, the concentration of serum syndecan-1 has been found to be associated with clinical outcomes in patients with heart failure and preserved ejection fraction." (PMID 34879094, 2021). "Additionally, it has been suggested that syndecan-1 is associated with left ventricular hypertrophy in heart failure with preserved ejection fraction." (PMID 34879094, 2021). "Furthermore, adrenaline was independently associated with short-and long-term mortality and heart failure (HF), and syndecan-1 was independently associated with long-term mortality." (PMID 23433357, 2013). "Furthermore, adrenaline and syndecan-1 were weakly but independently associated with mortality and heart failure." (PMID 23433357, 2013). "Patients with ischemic heart disease or heart failure with preserved ejection fraction (HFpEF) had higher serum syndecan-1 that correlated with the degree of inflammation and faster leukocyte recruitment." (PMID 38785504, 2024). "SDC-1 was reported to function in heart failure by promoting fibrosis through TGF-β/Smad2 or p38/MAPK pathway." (PMID 36078037, 2022). "The serum syndecan-1 concentration in patients with heart failure in this study was 72.4 ng/mL at admission, which peaked to 101.21 ng/mL on day 3 of admission." (PMID 34879094, 2021). "Differences in syndecan-1 concentrations among patients with different origins of heart failure are shown in S1 Table and those among patients with heart failure due to different medications are shown in S2 Table." (PMID 34879094, 2021). "Low CK and BUN concentrations also appeared to modify the relationship due to heart failure in patients with low syndecan-1 concentration." (PMID 34879094, 2021). "Achieving readmission-free survival for patients with heart failure with high syndecan-1 concentration was simple in the present study because the systemic fluid volume was abundant, despite the patients having received the treatment." (PMID 34879094, 2021). "Serum syndecan-1 concentration was analyzed in 152 patients who were hospitalized for worsening heart failure from September 2017 to June 2018." (PMID 34879094, 2021). "This study investigated the prognostic value of serum syndecan-1 concentration in patients with heart failure upon admission." (PMID 34879094, 2021). "In this paper, we aim to evaluate some perspectives on syndecan-1's role in the study of heart failure in patients with chronic liver disease." (PMID 31815014, 2019). "There is growing evidence highlighting the importance of syndecan-1 as an emerging biomarker for the diagnosis and prognosis of heart failure and also in the noninvasive assessment of liver fibrosis." (PMID 31815014, 2019). "Due to the growing interest in this biomarker, multiple studies aimed at revealing syndecan-1's potential benefits in the diagnosis and prognosis assessment in patients with heart failure or chronic liver disorders." (PMID 31815014, 2019). "In conclusion, serum syndecan-1 concentrations, which may indicate injury to the endothelial glycocalyx, can predict readmission-free survival in patients with heart failure." (PMID 34879094, 2021). "In brief, syndecan-1 may be a perceptive marker for assessing the state of volume overload through the state of heart failure." (PMID 34879094, 2021).